MMP17 (matrix metallopeptidase 17)
Description:
Endopeptidase that degrades various components of the extracellular matrix, such as fibrin. May be involved in the activation of membrane-bound precursors of growth factors or inflammatory mediators, such as tumor necrosis factor-alpha. May also be involved in tumoral process. Cleaves pro-TNF at the '74-Ala-|-Gln-75' site. Not obvious if able to proteolytically activate progelatinase A. Does not hydrolyze collagen types I, II, III, IV and V, gelatin, fibronectin, laminin, decorin nor alpha1-antitrypsin.
Synonyms: MMP-17; MTMMP4; MT4-MMP; MT4MMP
Tractability: Small molecule: a high-quality ligand is known; it belongs to a druggable protein family. Antibody: UniProt places it where antibodies can reach, with medium confidence; UniProt predicts a signal peptide or a membrane-spanning region; its Gene Ontology location is reachable by antibodies, with medium confidence. PROTAC: its protein half-life has been measured; a small molecule that binds it is known.
Target class: Metallo protease; Metallo protease M10A subfamily; Metallo protease MAM clan; Protease; Enzyme
Gene: Protein-coding gene on chromosome 12 (131,828,393 to 131,851,783, forward strand). Ensembl gene ENSG00000198598.
Subcellular location: Cell membrane (Isoform Long); Secreted, extracellular space, extracellular matrix
Pathways (Reactome):
Extracellular matrix organization: Activation of Matrix Metalloproteinases
Gene Ontology:
Molecular function: enzyme activator activity; metalloaminopeptidase activity; metalloendopeptidase activity; zinc ion binding; metallopeptidase activity
Biological process: collagen catabolic process; extracellular matrix organization; proteolysis
Cellular component: extracellular matrix; plasma membrane
Genetic constraint (gnomAD): Loss-of-function variants: 54 observed, 46.44 expected, observed/expected ratio (o/e) 1.16, 90% interval 0.93 to 1.46. The upper end of that interval is the gene's LOEUF score, 1.46, which puts it in group 6 of 6, group 1 being the genes least tolerant of losing a copy. Missense variants: 787 observed, 758.31 expected, observed/expected ratio (o/e) 1.04, 90% interval 0.98 to 1.1. Synonymous variants: 367 observed, 329.65 expected, observed/expected ratio (o/e) 1.11, 90% interval 1.02 to 1.21.
Homologues: Orthologues: chimpanzee MMP17 (99% identical), macaque MMP17 (96% identical), pig MMP17 (85% identical), dog MMP17 (84% identical), rat Mmp17 (83% identical), mouse Mmp17 (82% identical), guinea pig MMP17 (79% identical), tropical clawed frog mmp17 (67% identical), zebrafish mmp17a (60% identical), Caenorhabditis elegans zmp-3 (22% identical), Caenorhabditis elegans zmp-4 (20% identical), Caenorhabditis elegans Y50D7A.13 (12% identical), and 2 more. Paralogues in human: MMP25 (43% identical), MMP15 (32% identical), MMP14 (32% identical), MMP16 (32% identical), MMP24 (32% identical), MMP3 (29% identical), MMP2 (28% identical), MMP10 (27% identical), MMP11 (27% identical), MMP27 (27% identical), MMP1 (27% identical), MMP13 (27% identical), and 11 more.
Diseases named in the same sentence as MMP17 in open-access papers:
MMP17 is named in the same sentence as 45 diseases in open-access papers, as found by Europe PMC text mining. Sharing a sentence is not in itself a finding about the gene and the disease. The quoted sentences say what the papers report.
breast carcinoma (10 papers, 2009 to 2022). "MMP17 is a protein-coding gene that is associated with diseases such as breast cancer, colon cancer, and head and neck cancer." (PMID 34587931, 2021). "High expression levels of MMP17 have been associated with invasiveness of breast cancer, where inhibition of its expression by small interferring RNAs resulted in a non-invasive phenotype." (PMID 22102859, 2011). "MMP17 was implicated as a protease critical for breast cancer metastasis in animal models." (PMID 32575583, 2020). "MMP17 has been implicated in breast cancer as a positive modifier of EGFR signalling." (PMID 28120820, 2017). "Also, MMP17 was already likened to breast cancer, promoting tumor growth." (PMID 36313646, 2022). "In line with our screen data, Usp7, Metap1, Metap2, and MMP17 could be validated as depletion hits in vitro, whereby targeting reduced MTT viability and competitive breast cancer cell growth." (PMID 36313646, 2022). "It has been shown that miR-6775-3p can negatively regulate CDK4, CDK6, MMP17, and MMP24 levels in breast cancer cells by binding to the 3′UTR of their mRNAs, thereby inhibiting the proliferation, migration, and invasive abilities of breast cancer cells." (PMID 35891968, 2022). "No involvement of MMP-17 in the EMT of HCC was found in the literature, but it was implicated in breast cancer progression, apparently by facilitating in vivo and in vitro breast cancer cell proliferation through outside-in EGFR signaling, but without acting as a protease." (PMID 31886121, 2019).
Arthritis (2 papers, 2021 to 2022). Inflammation of a joint. "MMP15 and MMP17, as HUB genes, are involved in embryonic development, reproduction, and tissue damage recovery during normal physiological processes, however, they promote inflammation, such as arthritis and fibrosis, when the disease occurs." (PMID 35754546, 2022). "Additionally, MMP-17 mediates C-terminal processing of ADAMTS4, one of the aggrecanases that are thought to play a role in arthritis." (PMID 34255809, 2021).
colitis (2 papers, 2021 to 2023). Inflammation of the colon. "In a previous study, we reported that Mmp17 KO mice were highly susceptible to DSS-induced colitis." (PMID 37869014, 2023). "We recently demonstrated that mice lacking the membrane-bound matrix metalloproteinase MMP17 display impaired intestinal regenerative capacities in both a chemically-induced colitis and whole-body irradiation injury models." (PMID 37869014, 2023). "To test if smooth muscle, and in particular MMP17, could play a role in intestinal injury responses, we used dextran sulfate sodium (DSS) to induce experimental colitis and compare WT to KO littermates." (PMID 34795242, 2021).
colon cancer (2 papers, 2021 to 2023). "Not only in SOC, the elevated proteins of PER1, AKAP12 and MMP17 are also associated with the migration and invasion in triple-negative breast cancer, melanoma and colon cancer." (PMID 37434173, 2023).
lung carcinoma (2 papers, 2021). "In the present study, we identified two important MMPs, MMP1 and MMP17, that are the direct target genes of miR‐558 in lung cancer cells." (PMID 33190405, 2021). "In future studies, the hsa_circ_0030998/miR‐558/MMP1/MMP17 pathway will be further confirmed and clarified through a series of in vivo experiments and through studies in more lung cancer cells." (PMID 33190405, 2021). "In our study, we found that miR‐558 has binding sites for MMP1, MMP16, MMP17, and MMP24 3'‐UTRs, and only MMP17 and MMP1 were demonstrated to be significantly downregulated by miR‐558 through targeted regulation in lung cancer cells." (PMID 33190405, 2021).
triple-negative breast carcinoma (2 papers, 2023 to 2025). An invasive breast carcinoma which is negative for expression of estrogen receptor (ER), progesterone receptor (PR), and human epidermal growth factor receptor 2 (HER2). "For example, MMP-17 notably increases the sensitivity of tumors to Erlotinib and Palbociclib combination therapy in triple-negative breast cancer." (PMID 39994761, 2025).
aortic aneurysm (1 paper, 2023). A ruptured aneurysm located in the wall of the proximal portion of the descending aorta proceeding from the arch of the aorta. "Although MMP17 has not been directly linked to PAH, loss of function variants, found in familial studies, confer a greater risk of aortic aneurysm in mice through dysfunctional ECM filament deposition and an enlarged aortic lumen." (PMID 37066790, 2023).
atrophic gastritis (1 paper, 2015). "The expression of MMP17 in the normal gastric and atrophic gastritis tissues was significantly lower than that in the gastric cancer tissues (P<0.05)." (PMID 25621036, 2015). "The expression of MMP17 in the normal gastric and atrophic gastritis tissues was significantly lower than that observed in the gastric cancer tissues." (PMID 25621036, 2015). "However, the expression of MMP17 in the gastric cancer specimens was significantly higher than that in the normal and atrophic gastritis tissues (31/42 cases; χ12=38.74; χ22=34.10; P<0.05)." (PMID 25621036, 2015). "Immunohistochemistry and reverse transcription-quantitative polymerase chain reaction were used to detect the expression of MMP17 and MMP25 in 42 cases of gastric carcinoma and normal tissues, and 40 cases of atrophic gastritis." (PMID 25621036, 2015). "The present study compared the expression of MMP17 and MMP25 in gastric carcinoma, atrophic gastritis and normal gastric tissues." (PMID 25621036, 2015).
colorectal cancer (1 paper, 2021). A primary or metastatic malignant neoplasm that affects the colon or rectum. "This study implied that MMP11, MMP14, MMP17, and MMP19 are potential targets of precision therapy for patients with colorectal cancer." (PMID 34804973, 2021). "MMP1–MMP4, MMP7–MMP14, and MMP24 were significantly upregulated in colorectal cancer samples, while MMP15, MMP17, MMP19, and MMP24–MMP28 were significantly downregulated in colorectal cancer samples." (PMID 34804973, 2021). "Also, MMP11, MMP14, MMP17, and MMP19 are potential targets of precision therapy for patients with colorectal cancer." (PMID 34804973, 2021). "The transcriptional level of MMP17 and MMP19 in colorectal cancer tissue and normal tissue may need to be further confirmed." (PMID 34804973, 2021).
COVID-19 (1 paper, 2023). A disease caused by infection with severe acute respiratory syndrome coronavirus 2. "One molecule that is of interest here is the MMP17 gene, as this is a matrix metalloproteinase gene, and there is evidence to show that other matrix metalloproteinase molecules are related to neurological complications resulting from COVID-19." (PMID 37308820, 2023).
gastric cancer (1 paper, 2015). A primary or metastatic malignant neoplasm involving the stomach. "The MMP17-positive cells had a scattered or nest-like distribution in the gastric cancer tissues, and were markedly expressed on the edge of the cancer nest." (PMID 25621036, 2015). "The expression of MMP17 in advanced gastric carcinoma was revealed to be higher than that in early-stage disease (21/24 and 10/18 cases; t=2.437; P<0.05)." (PMID 25621036, 2015). "In addition, as gastric cancer is a multi-factorial and multi-linkage disease, the specific role of MMP17 in disease progression warrants further investigation." (PMID 25621036, 2015). "The present study demonstrated that MMP17 protein and mRNA expression was associated with the depth of tumor invasion, lymph node metastasis and serosal involvement of the gastric cancer patients (P<0.05), but not with age, gender, lesion length or histological grade (P>0.05)." (PMID 25621036, 2015). "Therefore, further analysis is required to determine whether MMP17 expression in gastric cancer exhibits regional differences." (PMID 25621036, 2015). "Furthermore, the detection of MMP17 may be of clinical value for the prognosis of patients with gastric cancer." (PMID 25621036, 2015). "In conclusion, the expression of MMP17 and MMP25 was increased in the gastric cancer tissues in the present study." (PMID 25621036, 2015). "The aim of the present study was to investigate the expression and clinicopathological features of matrix metalloproteinase 17 (MMP17; also known as MT4-MMP) and MMP25 (also known as MT6-MMP) in gastric cancer." (PMID 25621036, 2015). "The data from the present study demonstrated that the GPI-MT-MMPs MMP17 and MMT25, similar to other MT-MMPs, are highly expressed in gastric carcinoma." (PMID 25621036, 2015). "The detection of MMP17 and MMP25 expression may have clinical value in predicting the prognosis of patients with gastric cancer." (PMID 25621036, 2015). "Therefore, this indicates that the expression of MMP17 and MMP25 is increased with the degree of progress of gastric carcinoma." (PMID 25621036, 2015).
glioma (1 paper, 2020). A benign or malignant brain and spinal cord tumor that arises from glial cells (astrocytes, oligodendrocytes, ependymal cells). "In line with this, a recent paper used the TCGA data and found that expression levels of MMP16 and MMP17 in gliomas were in the top two of all cancers." (PMID 32872536, 2020). "The GPI-anchored human MMP17 is expressed in various glioma cell lines and digests a number of ECM constituents as well as TNF." (PMID 32872536, 2020).
helminth infection (1 paper, 2023). "Together, our data suggest that MMP17 extrinsically alters goblet cell maturation which is sufficient to alter clearance in a helminth infection model." (PMID 37869014, 2023).
Infertility (1 paper, 2023). "Additionally, POLR2J3, MMP17, MED17, and GATAD2A are associated with various conditions ranging from infertility to neuroinflammation." (PMID 38681774, 2023). "Upregulation of genes such as POLR2J3, MMP17, and MED17 provides insights into SARS-CoV-2 pathogenesis, suggesting potential links to conditions like infertility, cancers, and neuroinflammation." (PMID 38681774, 2023).
intestinal infections (1 paper, 2023). "We hypothesized that elevated levels of the effectors we observe in mice lacking MMP17, might offer an advantage in clearing intestinal infections, as both ANG4 and RELM-β have been described to have anti-bacterial properties." (PMID 37869014, 2023).
intestinal tumors (1 paper, 2021). "These morphological changes resemble those found in intestinal neoplastic lesions, so we next decided to evaluate the impact of Mmp17 loss in the initiation and progression of intestinal tumors using the ApcMin mouse model." (PMID 34795242, 2021).
lymph node metastasis (1 paper, 2015). "Furthermore, it was identified that MMP17 expression was elevated in patients with lymph node metastasis and serosal involvement." (PMID 25621036, 2015).
metastasis (1 paper, 2015). The spread or migration of cancer cells from one part of the body (where they first appeared) to another. "It was identified that the expression of MMP17 and MMP25 was significantly associated with the depth of tumor invasion, lymph node metastasis and serous membrane involvement, but not with patient age and gender, or lesion length, site and histological grade." (PMID 25621036, 2015).
open-angle glaucoma (1 paper, 2024). Chronic outflow obstruction of the eye's drainage canals that can lead to increased internal eye pressure and optic nerve damage. "Ussa and co-workers investigated whether the SNPs of the genes encoding MMP1, MMP2, MMP3, MMP9, and MMP17 were related to the response to latanoprost in 124 Spanish patients with open-angle glaucoma." (PMID 39769228, 2024).
ovarian serous tumor (1 paper, 2023). A benign, borderline, or malignant epithelial tumor of the ovary characterized by the presence of neoplastic epithelial cells that, in well differentiated tumors, resemble the epithelial cells of the fallopian tube and, in poorly differentiated tumors, show anaplastic features. "The validation experiments showed that the mRNA of PER1, AKAP12, and MMP17 was highly expressed in normal ovarian epithelial cells compared to SOC cell lines and there was a positive correlation between protein levels of PER1, AKAP12 and MMP17 and metastasis in human ovarian serous tumors." (PMID 37434173, 2023).
periodontal disease (1 paper, 2021). "Interestingly, Membrane-type matrix metalloproteinase 4 (MMP-17), Stromelysin-3 (MMP-11) and Epilysin (MMP-28) were consistently clustered with various GO terms associated with ECM remodeling and catabolism and have not been associated with periodontal disease to date." (PMID 34255809, 2021).
prostate carcinoma (1 paper, 2019). A carcinoma that arises from epithelial cells of the prostate gland. "The prostate cancer cell lines PC-3 and DU145 show high RNA expression for MMP17." (PMID 31888257, 2019).
Sepsis (1 paper, 2023). Sepsis is defined as life-threatening organ dysfunction caused by a dysregulated host response to infection. "Our study specifically highlights the differential expression of matrix metalloproteinases (MMPs), such as Mmp2-3, Mmp8-9, Mmp14, Mmp17, Mmp19, and Mmp28-29, with significantly higher expression in LPS-induced sepsis compared to CLP-induced sepsis." (PMID 37510271, 2023).
skin cutaneous melanoma (1 paper, 2023). "In general, the expression of MMP2, MMP13, MMP16, MMP17 and MMP25 were significantly associated with skin cutaneous melanoma (SKCM) patients prognosis, among which MMP2 low expression benefited patients the most." (PMID 36788565, 2023).
uterine corpus endometrial carcinoma (1 paper, 2025). A endometrial carcinoma (disease) that involves the body of uterus. "In a more recent study, the expression of MMP11 and MMP17 in uterine corpus endometrial carcinoma (UCEC) was determined, and bioinformatics tools were used to correlate their expression with patient prognosis, as they influence immune cell infiltration." (PMID 41228294, 2025). "Moreover, MMP11 and MMP17 were suggested as potential biomarkers for the prognosis of uterine corpus endometrial carcinoma." (PMID 41228294, 2025).